ASPG (asparaginase)
Diseases named in the same sentence as ASPG in open-access papers (continued):
Sharing a sentence is not in itself a finding about the gene and the disease.
tumor (continued). "In this study, we evaluated three novel drug classes in our Tsc2-/- subcutaneous tumor model: an enzyme that interferes with amino acid metabolism (asparaginase), two VEGF inhibitors (sunitinib and bevacizumab), and a microtubule inhibitor (vincristine)." (PMID 20146790, 2010). "In order to evaluate the utility of some novel drug classes for the treatment of TSC related tumors, we investigated the efficacy of asparaginase, sunitinib, bevacizumab, and vincristine in treating a relevant subcutaneous tumor model." (PMID 20146790, 2010). "However, depletion of CD8+ T cells (Asparaginase + anti-PD-L1 + anti-CD8 group) significantly diminished the anti-tumor efficacy of the combination therapy, resulting in tumor growth rates significantly faster than the Asparaginase + anti-PD-L1 group." (PMID 41229436, 2025). "Furthermore, the average tumor volume in the combination therapy group was significantly reduced compared to either the asparaginase monotherapy group or the anti-PD-L1 monotherapy group." (PMID 41229436, 2025). "Indeed, the combination of asparaginase and anti-PD-1 induced the most potent antitumour responses compared with individual treatment in both tumour settings." (PMID 40045118, 2025). "Assessment of tumor weight at the end of the treatment period showed average tumor weights control group were 658.75 ± 109.94 mg, asparaginase group were 500.00 ± 84.41 mg, anti-PD-L1 group were 396.25 ± 95.78 mg, and combination therapy group were 167.51 ± 21.65 mg." (PMID 41229436, 2025). "Given that STm asparaginase could also antagonise tumour c-Myc expression, effecting organoid growth and Lgr5 expression, we now questioned how protective the STmΔaroA/ΔansB double mutant would be in vivo." (PMID 39558103, 2024). "The results showed that, regardless of risk stratification, asparaginase truncation did not increase tumour relapse or death risk in children with ALL." (PMID 39439952, 2024). "Despite this, the use of STm∆aroA also lacking asparaginase reduced tumour burden in a model of colitis-associated CRC." (PMID 39558103, 2024). "Thus, in treatments using asparaginase to regulate asparagine levels, its reduction and indirect impact on glutamine levels can profoundly affect tumor dynamics." (PMID 39050845, 2024). "Asparaginase produces its anti-tumor effects by converting the protein asparagine to aspartic acid." (PMID 35328487, 2022). "A previous study identified that elevated Asp levels serve as an endogenous metabolite, supporting tumor growth via conversion of Asn to Asp by asparaginase activity and maintenance of Asp pools by electron acceptor activity was found to support cell proliferation." (PMID 33762012, 2021). "Moreover, mechanisms mediating resistance to asparaginase should be clarified in order to maximizing the tumor killing effect of asparaginase and discovering novel therapeutic targets." (PMID 33391513, 2021). "One might hypothesize that ASNS, asparaginase, and autophagy exist in a fine balance that maintains control of asparagine homeostasis in tumor cells." (PMID 31681605, 2019). "In addition, in tumor xenograft model using U87MG cell line, the combination treatment of asparaginase and CQ significantly reduced the tumor volume and tumor weight." (PMID 29207624, 2017). "Asparaginase-induced depletion of circulating asparagine and glutamine might ultimately induce cell death by affecting both tumor energy metabolism and macromolecular biosynthesis." (PMID 24349380, 2013). "Asparagine synthetase, the enzyme responsible for synthesis of asparaginase, may be differentially expressed in tumour cells contributing to poor L-ASP activity." (PMID 22333033, 2012). "To test whether asparaginase could directly antagonise tumour growth, we added E. coli-derived asparaginase to tumours and measured growth by MTT, showing a dose-dependent halting of tumour metabolism, indicating that intestinal tumour organoids are sensitive to asparagine depletion." (PMID 39558103, 2024).
tumor (continued). "High ASNS expression may contribute to asparaginase resistance of tumor cells." (PMID 36405587, 2022). "Thus, this in vivo study verified that BCYRN1 could lead to resistance of ENKTCL to asparaginase by enhancing autophagy of tumor cells." (PMID 33391513, 2021). "Given that mounting studies have suggested that GLS1 inhibition or blocking ASNS in combination with asparaginase treatment is effective in attenuating tumor growth, targeting GLS1 and ASNS could be promising therapeutic strategies to suppress cancer progression through impairing angiogenesis." (PMID 33117704, 2020). "However, the anti-tumor effect of asparaginase is always restricted due to complicated mechanisms." (PMID 29207624, 2017). "In contrast, DAPK1, ASPG, and CPA3 were more highly expressed in normal tissues than in tumor tissues." (PMID 41425595, 2025). "Therefore, from the perspective of the impact of asparaginase withdrawal on haematological tumour relapse, for children with intermediate and high-risk ALL, the potential dangers of being re-exposed to asparaginase must be carefully weighed against the need for asparaginase to ensure survival." (PMID 39439952, 2024). "R=0.817, p=6.3 × 10–5) but not in vehicle (R=0.131, p=0.758) or DTX (R=0.397, p=0.158) treated tumours, suggesting that ATF4 specifically drives asparaginase-induced Asns expression." (PMID 36525288, 2022). "Cross-linker-free poly (lactic co-glycolic acid-based nanoformulation), loaded with asparaginase, was another efficient means that reduced the EAT tumor volume by 50%." (PMID 35744957, 2022). "Eight patients (N = 8) received chemotherapy as tumor debulking therapy prior to HSCT, including CHOP, R–CHOP plus etoposide, doxorubicin, pralatrexat, vorinostat, gemcitabine, asparaginase, ifosfamide and DHAP (dexamethasone, high-dose AraC, platinol)." (PMID 32714935, 2020). "We observed that asparaginase treatment led to a robust reduction of tumour burden in wild-type mice but failed to suppress tumour cell growth in TCRb knockout (KO) mice." (PMID 40045118, 2025). "MFC tumor-bearing mice models were established, and mice were assigned to the following treatment groups: Control, Asparaginase + anti-PD-L1, Asparaginase + anti-PD-L1 + anti-CD4, and Asparaginase + anti-PD-L1 + anti-CD8." (PMID 41229436, 2025). "We found that Salmonella additionally lacking asparaginase also had a significant reduction in tumour load, indicating that STmΔaroA/ΔansB is still capable of reducing tumour growth in vivo." (PMID 39558103, 2024). "Indeed, we previously tested the sorption ability of asparaginase EwA and its conjugates with PEG-chitosans on tumor cells." (PMID 35455403, 2022). "Unlike the prominent growth inhibition in vitro, asparaginase alone hardly exhibited anti-tumor effect in vivo." (PMID 29207624, 2017). "The nutritional stress induced by asparaginase by depletion of serum and CSF asparagine leads to DNA, RNA and protein biosynthesis inhibition in ALL, AML and other asparagine dependent tumor cells, resulting in subsequent apoptosis due to cell cycle arrest in G0/G1 phase." (PMID 26891220, 2016). "Single agent asparaginase is not as effective as rapamycin at decreasing tumor volume or increasing survival." (PMID 20146790, 2010). "Moreover, B16-OVA tumour-bearing mice treated with asparaginase before the transfer of tumour-specific OT-1 CD8+ T cells, completely impede tumour growth, highlighting that the quality of tumour-reactive CD8+ T cells can be modulated in response to asparaginase treatment." (PMID 40045118, 2025). "In vivo, STm lacking the asparaginase still controls tumour growth." (PMID 39558103, 2024). "ASP-liposomes that contained encapsulated asparaginase did not inhibit the growth of the studied tumor cells (inhibition < 1%), possibly due to a slow liposome degradation that prevents asparaginase release or to an instability of the released enzyme, with a subsequent loss of catalytic activity." (PMID 34681778, 2021).
tumor (continued). "Notably, the off-target glutaminase (GLS) activity of asparaginase is not required for its anti-tumour effects." (PMID 27126896, 2016). "The slightly lower median survival in the asparaginase plus rapamycin combination group suggests that adding asparaginase to rapamycin may enhance tumor growth in some cases, although the mechanism is not known." (PMID 20146790, 2010). "This is consistent with the results of a previous study where presentation EBV DNA levels did not have an impact on survival independently, implying that the sensitivity of the tumor to asparaginase-based therapy, rather than its load, might be a more important indicator of survival." (PMID 26210287, 2015). "We also found that angiogenesis inhibitors and asparaginase reduce tumor growth in a TSC2 tumor mouse model and although these drugs are not as effective as rapamycin, these drug classes may have some therapeutic potential in the treatment of TSC related tumors." (PMID 20146790, 2010). "Unlike asparaginase, LO has a dual mechanism of action: depletion of L-lysine and formation of H2O2, both targeting tumor growth." (PMID 34832852, 2021).
infection (12 papers, 2013 to 2026). The state of being infected such as from the introduction of a foreign agent such as serum, vaccine, antigenic substance or organism. "Chemotherapeutic drugs, such as carboplatin, melphalan, busulfan, and asparaginase, were also related to higher risk of this infection." (PMID 36921180, 2023). "According to transcriptomic data on infected cells from different zones of pea nodules, the asparaginase gene demonstrated 14-fold downregulation in the nitrogen-fixing cells compared to the cells from the infection zone." (PMID 38138973, 2023). "Collectively, available results indicate that the competitive utilization of asparagine by pathogens via asparagine synthetase, asparagine transporter, and asparaginase has important influences on the pathogenesis of infection and the outcome of an infection." (PMID 29535717, 2018). "Typhi ansB, encoding an asparaginase, prevented ISR activation during infection." (PMID 42294633, 2026). "Furthermore, the coinjection of exogenous asparaginase during the infection of fly hosts with LSMMG-reared S. marcescens, results in a therapeutic effect and the flies die more slowly than with injections of the LSMMG-treated bacteria alone." (PMID 35592661, 2022). "Increasing the amount of asparagine and decreasing the amount of aspartic acid by inhibiting asparaginase enzyme, could enhance the inhibitory effect of phagolysosome fusion and consequently inhibit promastigotes infection in the host body." (PMID 31543914, 2019). "As happened in vitro, RNAi revertants appeared during the course of infection in asparaginase-treated, but not untreated, mice." (PMID 24340117, 2013). "The lack of induction of the sole asparaginase gene ansA (BCG1590c; Rv1538c), that can catalyze the conversion of asparagine to aspartate, suggests that, in addition to its reported asparagine transport capacity, mycobacterial AnsP2 imports aspartate from the phagosome during infection." (PMID 25649146, 2015).
hematologic malignancies (6 papers, 2014 to 2025). "Secondly, asparaginase depletion using L-asparaginase has been a very effective approach in treating hematologic malignancies with detailed toxicity profile and well-studied resistance mechanism." (PMID 28750681, 2017). "Pegaspargase is a pegylated asparaginase formulation used in hematological malignancies." (PMID 41316157, 2025). "Recently, it has been reported that asparaginase also showed ideal therapeutic effects in other hematological malignancies, while its effect on solid tumors is not so ideal." (PMID 41316157, 2025). "Blood disorders were the most frequent ADR (96; 32.8%), related to thioguanine and pegaspargase mainly, followed by infections (86; 29.4%) related to thioguanine, pegaspargase, Erwinia asparaginase and rituximab." (PMID 34025429, 2021).
adenocarcinoma (1 paper, 2024). A common cancer characterized by the presence of malignant glandular cells. "•Asparaginase inhibits proliferation of two adenocarcinoma cell lines." (PMID 39170541, 2024). "•Asparaginase can have a cytostatic effect on adenocarcinoma cells." (PMID 39170541, 2024).
ASPG also shares sentences with these, for which no sentence is quoted: Hyperbilirubinemia (4 papers); non-Hodgkin lymphoma (3); Adrenal insufficiency (2); alcohol abuse (2); arterial hypertension (2); arteriopathy (2); gallstones (2); Glucose intolerance (2); hematologic cancers (2); Liver dysfunction (2); lymphoblastic lymphoma (2); peripheral neuropathy (2); prostate carcinoma (2); sinusoidal obstruction syndrome (2); Thromboembolism (2); anemia (1); asthma (1); bacterial diseases (1); bladder cancer (1); blood cancer (1); childhood cancer (1); childhood leukemia (1); cholangiocarcinoma (1); cholestasis (1); chronic lymphocytic leukemia (1); CNS tumor (1); colitis (1); endocrinopathies (1); endometriosis (1); ependymoma (1).
A further 36 diseases each share a sentence with ASPG in 1 paper.